BDNF (brain derived neurotrophic factor)
Diseases named in the same sentence as BDNF in open-access papers (continued):
Sharing a sentence is not in itself a finding about the gene and the disease.
Rett syndrome (continued). "This dosing regimen was based on previous work in a mouse model of Rett’s syndrome, where fingolimod (0.1 mg/kg i.p.)administration every 4 days for 2–4 weeks improved motor behavior and increased striatal and cortical BDNF levels." (PMID 41516369, 2026). "BDNF appears to be involved in the initiation and progression of the Rett syndrome phenotype in mice." (PMID 39888294, 2025). "Recent findings have indicated that neurotrophic factors such as BDNF can serve as potential therapeutic candidates in neurodevelopmental disorders such as Rett syndrome and CDD." (PMID 39592934, 2024). "More recently, a report used the CRISPR-Cas system to engineer Brain-Derived Neurotrophic Factor (BDNF)-overexpressing MSCs that were applied to effectively treat Rett syndrome in an experimental mouse model." (PMID 35631698, 2022). "The modulation of BDNF pathways has been suggested as a potential strategy for treating children with Rett syndrome." (PMID 35916975, 2022). "Environmental enrichment with a music-based intervention or sensory stimulation can increase the serum BDNF level and improve social interactions in patients with early stage Rett syndrome." (PMID 34281226, 2021). "Our data provide evidence that music-based interventions can restore the social abilities of Rett syndrome (RTT)mice through the upregulation of BDNF mRNA expression in the prefrontal cortex and an increase in the BDNF protein level in the hippocampal region." (PMID 34281226, 2021). "HDACs have been suggested as therapeutic targets for Rett Syndrome and HDAC6 inhibition has been linked to improved BDNF trafficking in a Rett mouse model." (PMID 34355696, 2021). "BDNF is one of the most prominent deregulated factors in Rett syndrome, a severe neurodevelopmental disorder." (PMID 31913581, 2020). "New drug, cell and gene therapies for neurological disorders including Rett syndrome are being developed that use BDNF pathways." (PMID 29321033, 2018). "This study examined the effects of environmental enrichment on gross motor skills and BDNF protein levels in Rett syndrome." (PMID 29321033, 2018).
Rett syndrome (continued). "We investigated the effects of environmental enrichment on gross motor skills and blood BDNF levels in girls with Rett syndrome." (PMID 29321033, 2018). "Secondly, FTY720 restored normal BDNF expression levels in the brain in a mouse model of Rett syndrome and in mice injected with Aβ, ameliorating locomotor and cognitive functions, respectively." (PMID 25953296, 2015). "Therapies are currently being developed that will aid in restoring BDNF abnormalities to normal, thereby slowing the progression of diseases like Huntington's and Rett syndrome." (PMID 22720171, 2012). "Increased expression of BDNF, measured by Western blots, BDNF-GFP, or ELISA, caused improvements in synaptic function, dendrite length, and respiratory function in Rett syndrome mouse models." (PMID 22720171, 2012). "Current studies in our laboratory use BDNF-pHluorin to study activity-dependent BDNF release in neurons from a mouse model of Rett syndrome." (PMID 22720171, 2012). "A role for BDNF in Rett syndrome has also been described, suggesting that dysregulation of the BDNF gene may affect the severity of this pathology." (PMID 37446337, 2023). "Moreover, administration of fingolimod, a sphingosine-1 phosphate analogue, effectively increases BDNF levels by inducing the activation of the TrkB-MAPK-CREB pathway in a mouse model of Rett syndrome." (PMID 37238659, 2023). "Rett syndrome (RTT) is a developmental disorder with an alteration in the transport of BDNF." (PMID 33374719, 2020). "There is some clinical evidence of a role for BDNF in Rett syndrome pathogenesis." (PMID 29321033, 2018). "This interaction may also be related to Rett Syndrome, a disorder in which activity dependent BDNF transcription is hampered." (PMID 29915698, 2018).
Rett syndrome (continued). "BDNF levels vary with factors such as the time of the day and age, and further standardized assessment in children with Rett syndrome is necessary to understand BDNF production in Rett syndrome and explain any variance between different neurodevelopmental disorders." (PMID 29321033, 2018). "Recent MS research has turned to other white matter neurological disorders such as Rett Syndrome, to provide insight into the additional factors that may regulate the transcriptional expression of BDNF." (PMID 28604632, 2017). "Furthermore, FTY720-P injections induced BDNF production and improved disease symptoms in mouse models of Rett syndrome." (PMID 23593505, 2013). "Brain-derived neurotrophic factor (BDNF) levels are lower than expected in the nucleus tractus solitarius, which may correlate with abnormal neuronal gating and cardiorespiratory abnormalities in Rett syndrome." (PMID 31379529, 2019). "The overlapped clinical picture between KIF1-related disorders and Rett-like syndrome (psychomotor retardation/arrest, abnormal breathing pattern, stereotyped hand movements) may be due to the common target gene, neurotrophin-brain-derived neurotrophic factor (BDNF)." (PMID 37239332, 2023). "In a mouse model of Rett syndrome, fingolimod counteracted NMDA-induced neuronal death in a BDNF-dependent manner." (PMID 35250559, 2022). "Editors' choice: The brain-penetrant BDNF loop domain mimetic LM22A-4 improves synaptic plasticity and spatial discrimination memory in Rett syndrome mice, making it a promising therapeutic candidate for the treatment of hippocampal dysfunction." (PMID 28679669, 2017). "Exogenous BDNF is not a practical therapeutic choice for a neurodevelopmental disorder like Rett Syndrome as it does not cross the blood–brain barrier (BBB)." (PMID 33429932, 2021). "In contrast to previous studies using a mice model of Rett syndrome, our data showed that fingolimod did not restore the expression of mRNA BDNF in EAE mice." (PMID 25915660, 2015). "In the case of Rett syndrome, ERK signaling through the BDNF pathway in particular is reduced." (PMID 24238429, 2013). "Downregulation of the BDNF/TrkB signaling pathway with the decreased density of synapse and spine has been observed in certain ASD animal models, such as Rett syndrome (RTT) and VPA models." (PMID 37065903, 2023). "Moreover, in a recent trial evaluating fingolimod in patients with Rett syndrome (FINGORETT study), 12-month treatment with the drug did not lead to BDNF enhancement in children with Rett syndrome." (PMID 35250559, 2022).
psychosis (72 papers, 2012 to 2025). "This review aims to systematically examine and narratively synthesize the current evidence on peripheral BDNF levels in individuals at ultra-high risk for psychosis." (PMID 41008288, 2025). "By doing so, the review evaluates the potential of BDNF as a biomarker of risk for psychosis and its clinical course." (PMID 41008288, 2025). "Nevertheless, small studies with mixed findings of BDNF levels are reported concerning the high-risk state, however, its utility for predicting conversion to psychosis or treatment response is yet to be clarified." (PMID 37592817, 2024). "A more recent study examining 50 patients undergoing their first episode of psychosis showed that high TSH levels were associated with low peripheral BDNF and reduced hippocampal volume, suggesting a potential neuroprotective effect of THs on the hippocampus." (PMID 38911040, 2024). "Cognitive Behavioral Therapy (CBT) as an adjunctive to treatment-as-usual, in a group of eighty-six patients with first-episode psychosis, observed an increase in plasma BDNF levels associated with a decrease in general psychotic symptoms." (PMID 36767478, 2023). "miR-195 has been found to have a role in regulating BDNF, suggesting that, as well as the role of diagnostic biomarker, it is also involved in the mechanisms underlying psychotic disorders." (PMID 37760977, 2023). "GADD45β has been shown to regulate activity-dependent DNA demethylation at specific loci in genes like BDNF and fibroblast growth factor 1 (Fgf1) that have been implicated in neurogenesis, synaptic plasticity, and psychosis." (PMID 36781843, 2023). "In this study, we show the impact of various forms of therapy on BDNF levels and their association with clinical response in patients suffering from psychotic disorders." (PMID 36767478, 2023). "A decrease in BDNF has been strongly associated with psychosis in a number of neuropsychiatric disorders." (PMID 37712092, 2023). "BDNF-rs6265 has been associated with decreased hippocampal volumes in both healthy controls and patients experiencing first-episode psychosis." (PMID 36168994, 2022). "It should be noted that publications on BDNF and cognition in subjects considered at high risk of developing psychosis have begun to appear, but these studies are still scarce and include a relatively small number of subjects." (PMID 34220575, 2021). "We found three recent studies that investigated the relationship between peripheral blood levels of BDNF and cognition in subjects at risk of developing psychosis." (PMID 34220575, 2021). "For example, a significant correlation between the rs6265 polymorphism of BDNF and psychosis risk was found." (PMID 33384622, 2020). "An obvious association between the BDNF rs6265 genotype and the onset age of psychosis has also been demonstrated." (PMID 33384622, 2020). "In humans, frontocortical DNA methylation of the BDNF gene was correlated with a genotype that was associated with major psychosis in a genome-wide epigenomic study of major psychosis." (PMID 29991943, 2018). "Low serum BDNF levels have been linked to the onset of schizophrenic process and the duration of untreated psychosis, probably reflecting an association between BDNF and the pathogenesis of the disorder." (PMID 24551075, 2014). "There is a correlation between hippocampal volumes and serum BDNF levels, such that smaller hippocampal volumes in drug-naïve patients with first episode psychosis are associated with lower BDNF levels." (PMID 23320462, 2013). "Specifically, it compares peripheral BDNF levels among ultra-high-risk individuals, healthy controls, and patients with first-episode psychosis or chronic schizophrenia, to assess whether alterations are already detectable during the early or prodromal phase." (PMID 41008288, 2025). "However, findings on peripheral BDNF levels in individuals at ultra-high risk (UHR) for psychosis have been inconsistent." (PMID 41008288, 2025).
psychosis (continued). "This review synthesizes current evidence comparing peripheral BDNF levels in UHR populations with those in healthy controls (HCs), first-episode psychosis (FEP), and chronic schizophrenia (CS), focusing on BDNF’s potential relevance as a biomarker of psychosis risk and subsequent clinical course." (PMID 41008288, 2025). "We propose that the active phase of psychosis may be associated with an imbalance between BDNF forms, with a higher proportion of the pro-BDNF isoform." (PMID 41010622, 2025). "Hypersensitivity to psychostimulant administration in our study suggests BDNF may be implicated in mediating neuronal networks governing sensitisation development and psychosis and provides evidence for neurotrophic modulation of psychomotor behaviours." (PMID 37626786, 2023). "Furthermore, the lower peripheral level of BDNF in individuals with an at-risk mental state for psychosis compared to first-episode psychosis and chronic schizophrenia patients was investigated." (PMID 37047292, 2023). "Thus, BDNF has been proposed to play a role as an indicator of the risk of psychosis development and cognitive deficit in schizophrenia." (PMID 37047292, 2023). "Also, a high degree/likelihood of replication was found for the two GWAS- (ZNF804A and CACNA1C) and one candidate-implicated (BDNF) SNPs, which supports their involvement in psychosis and brain structure." (PMID 36168994, 2022). "Although it may be promising to use peripheral BDNF level as a diagnostic biomarker for psychosis, the specificity of this marker remains unclear." (PMID 35447946, 2022). "This review article focuses on recent BDNF studies in relation to cognition in human subjects during different stages of the psychotic process, including subjects at high risk of developing psychosis, patients at their first episode of psychosis, and patients with chronic schizophrenia." (PMID 34220575, 2021). "Positive associations between plasma BDNF levels and cognitive functions like learning capacity, verbal delayed memory, abstract verbal reasoning, and processing speed were also shown in first episode psychosis (FEP)." (PMID 31428035, 2019). "We investigated whether FKBP5 and BDNF genotype moderated the association between CT and two proxies of hippocampal integrity differently in individuals with a diagnosis of a psychotic disorder, compared to healthy siblings." (PMID 24658422, 2014). "Interestingly we have recently shown that stressful events can influence BDNF expression at the onset of psychosis, and that this association is possibly mediated by an inflammatory pathway." (PMID 22749891, 2013). "Nevertheless, the sample was large enough to suggest that BDNF and cognitive performance are associated, and that plasma BDNF levels after clinical stabilisation could be used as a biological marker of cognition in psychotic disorders." (PMID 23320462, 2013). "It is also difficult to determine the extent to which peripheral BDNF levels correlate with central BDNF levels; only one study has found a positive association between peripheral and central BDNF levels, and that study was conducted with people with psychosis." (PMID 32509348, 2020). "Two studies found significantly lower peripheral BDNF levels in UHR compared with patients with established psychosis." (PMID 41008288, 2025). "Consistent evidence indicates that individuals with first-episode psychosis (FEP) and chronic schizophrenia (CS) exhibit reduced peripheral BDNF levels, suggesting a link between neurotrophic deficits and the pathophysiology of psychotic disorders." (PMID 41008288, 2025). "One biomarker that has received considerable attention is brain-derived neurotrophic factor (BDNF), due to its well-documented involvement in neurodevelopment, synaptic plasticity, and cognitive function —processes known to be disrupted in psychosis." (PMID 41008288, 2025).